PGR (progesterone receptor)
Diseases named in the same sentence as PGR in open-access papers (continued):
Sharing a sentence is not in itself a finding about the gene and the disease.
tumor (continued). "There was no siginificant correlation with tumour stage, progesterone receptor status and Her2 expression." (PMID 22920283, 2012). "The outgrowth of triple negative “basal-like” tumor cells lacking the ER, progesterone receptor (PR), and human epidermal growth factor receptor 2 (HER2) is particularly concerning as patients with these tumors have a poor prognosis." (PMID 23231648, 2012). "Immunohistochemical (IHC) examinations of the tumor cells showed negative results for both estrogen receptor (ER) and progesterone receptor (PgR) and showed weak membrane staining of HER-2 (1+ score)." (PMID 22059982, 2011). "In multivariate analyses for OS both advanced tumor size (p = 0.01) and a lack of progesterone receptor expression were correlated (p = 0.01) with poor patients outcome in MBC." (PMID 21816051, 2011). "On immunohistochemical evaluation, the tumor cells were positive for epithelial membrane antigen, human epidermal cytokeratins, and progesterone receptor, but negative for calretinin, carcinoembryonic antigen, MCF-7 cell line (Ber-EP4), and estrogen receptor." (PMID 22937386, 2011). "In multivariate analyses for OS both advanced tumor size (p = 0.01) and a lack of progesterone receptor expression (p = 0.03) were correlated with poor patients outcome." (PMID 21816051, 2011). "The status of both ER and PgR was negative in 30% of cases whereas 27% of tumours showed HER2 overexpression." (PMID 22009030, 2011). "Progesterone receptor (PgR) was negative in 15 cases, positive in < 50% of the tumor cells in 12 cases and positive in > 50% of the tumor cells in 20 cases." (PMID 20976182, 2010). "The tumor is often high grade and estrogen and progesterone receptor negative, and has been found to be positive also for other molecular markers that are frequently associated with more aggressive tumor behavior." (PMID 20492657, 2010). "There was a significant correlation between PKCα staining intensity and lack of ER (p < 0.001) and progesterone receptor (PR; p = 0.002) as well as with tumor grade (p = 0.001) and proliferation rate (Ki-67; p < 0.001)." (PMID 20398285, 2010). "In pN+ patients, surgical tumour size of >20 mm (HR 3.59; P=0.004) and ER- and/or PgR-negative status (HR 2.92; P=0.001) were significantly related to higher metastasis risk, whereas none of these factors were related to the risk of metastasis in pN0 patients." (PMID 20197771, 2010). "Comparing tumours based on ER status, irrespective of molecular subtype, a higher methylation frequency was observed in ER-positive and progesterone receptor (PgR)-positive tumours (P = 0.005 and P = 0.02, respectively, t-test)." (PMID 20565864, 2010). "Gabarapl1 mRNA levels were found to be significantly lower in tumours presenting a high histological grade, with a lymph node-positive (pN+) and oestrogen and/or progesterone receptor-negative status." (PMID 20197771, 2010). "HJURP mRNA levels were significantly associated with estrogen receptor (ER), progesterone receptor (PR), Scarff-Bloom-Richardson (SBR) grade, age and Ki67 proliferation indices, but not with pathologic stage, ERBB2, tumor size, or lymph node status." (PMID 20211017, 2010). "Levels were not different by tumour size, grade, node involvement or oestrogen receptor, progesterone receptor, or human epidermal growth factor receptor 2 status." (PMID 20736944, 2010). "Our study found only one estrogen and progesterone receptor–negative (er−/pr−) tumour that was subsequently reported as er+/pr+." (PMID 20179800, 2010). "About 40% of tumor cells were positive for estrogen receptor (ER) and progesterone receptor (PgR), but negative for HER2, phenotypically corresponding to Luminal A type." (PMID 20731838, 2010). "In contrast, tumours that developed in mice implanted with MCF7S1 + HMF3s cells without oestrogen showed significant downregulation of PgR, a well-known downstream target of ER." (PMID 20723242, 2010).
tumor (continued). "ILC has distinct clinicopathological characteristics with a larger tumor at presentation, a lower HG, ER/PgR positive and HER2 negative status, and low Ki-67 expression, as compared to overall IDC." (PMID 21126378, 2010). "The prevailing paradigm suggests that lack of PgR tumor expression indicates disengaged ERα signaling and therefore concomitant loss of the ERα tumor growth signal and therapeutic target." (PMID 20550710, 2010). "The following biomarkers had results available in 95–100% of tumour samples: EGFR; HER2; ER; PgR." (PMID 19844234, 2009). "The tumor was estrogen and progesterone receptor negative and not amplified for the HER-2/neu gene via fluorescence in situ hybridization (FISH)." (PMID 19126225, 2009). "The level of expression has ranged from all tumor specimens being negative to 100% being positive for progesterone receptor." (PMID 19889208, 2009). "In our case the tumor was not more than 5 cm in greatest dimension, and tests for estrogen receptor, progesterone receptor, and Her-2 were negative." (PMID 19393076, 2009). "Vimentin-positive tumours affected younger women (p = 0.024), usually lacked estrogen and progesterone receptor (p < 0.001), more often expressed basal cytokeratins (<0.001), and were high-grade cancers (p < 0.001)." (PMID 19695088, 2009). "ILC generally had a lower histologic tumor grade and were more often estrogen receptor positive, progesterone receptor positive, and Her-2/neu negative." (PMID 19317888, 2009). "Immunohistochemically, the tumor cells in both the peripheral epithelial area and the central myxoedematous area were negative for estrogen receptor (ER), progesterone receptor (PgR) and Her2." (PMID 18559079, 2008). "Highly differentiated ER-positive or PgR-positive tumours were never completely eradicated with chemoendocrine treatment." (PMID 18380893, 2008). "The tumor was strongly positive for estrogen receptors (ER) and negative for progesterone receptors (PgR)." (PMID 18442419, 2008). "It is therefore possible that in tumours with a functioning ER (ER+/PgR+) ‘active’ c-Src is in the nucleus and not able to perform its role in promoting tumour progression." (PMID 19018258, 2008). "Patients with estrogen receptor–negative (er−)/progesterone receptor–negative (pr−) tumours were more likely to achieve pcr than were those with er+/pr+ tumours." (PMID 19079627, 2008). "Black women had a higher frequency of grade 3 tumours, lymph node-positive disease, negative oestrogen receptor and progesterone receptor status and basal-like (triple negative status) tumours." (PMID 18182985, 2008). "Total numbers vary due to differing numbers of cases with missing data for each variable; however, black patients had a greater frequency of grade 3 tumours, lymph node-positive disease and negative ER and PgR status, compared with white women." (PMID 18182985, 2008). "PgR expression is a marker of a functional ER and a number of laboratory studies have shown the importance of molecular characteristics such as PgR and HER2 in predicting tumour response to endocrine therapy." (PMID 19018258, 2008). "Immunohistochemical findings showed the tumor cells had the characteristics of both epithelial cells and mesenchymal cells, while being negative for estrogen receptor, progesterone receptor, Her2, myoepithelial cell markers and basal cell markers." (PMID 18559079, 2008). "At surgery, all tumours but one remained ER positive, whereas PgR switched to a negative phenotype in 25 out of 30 patients." (PMID 18941458, 2008). "The tubular/cribriform tumours were predominantly Her-2 negative (76.9%), ER positive (84.6%), and PgR negative (61.5%)." (PMID 17892570, 2007). "Elevated HER2 levels were not correlated with initial tumor size, estrogen receptor or progesterone receptor status, and localization of metastases (data not shown)." (PMID 17963511, 2007).
tumor (continued). "Although anecdotal responses have been observed in women with ER- and PgR-negative tumours, in current clinical practice, only postmenopausal women with ER-positive and/or PgR-positive tumours are selected for treatment with AIs." (PMID 17892469, 2007). "On the other hand, the in situ tumours were predominantly Her-2 negative (92.9%), and ER (85.7%) and PgR (71.4%) positive." (PMID 17892570, 2007). "There were no apparent expression differences related to grade, lymph node involvement, estrogen or progesterone receptor status, HER2 status or donor age; however, there appeared to be a threshold tumour size after which RBM6-RBM5 chimeric transcript expression was detectable." (PMID 17908320, 2007). "We found that the degree of immunohistochemical staining correlated significantly with nodal metastasis and tumor size but seems to be independent of other parameters such as age, grading and estrogen or progesterone receptor status." (PMID 17956604, 2007). "In contrast to tumour grade and mitotic index, most these cases were also PgR negative (67.4% and 76.9% respectively, p = 0.016)." (PMID 17892570, 2007). "AIs appear to be more effective than tamoxifen in ER-positive tumours regardless of PgR or growth factor receptor status." (PMID 17892469, 2007). "YKL-40 immunoreactivity significantly correlated with larger tumor size, poorer tumor differentiation, and a greater likelihood of being estrogen and/or progesterone receptor negative." (PMID 17286869, 2007). "The invasive tumours were predominantly Her-2 positive (87%), and ER (79.7%) and PgR negative (71%) (p < 0.0001)." (PMID 17892570, 2007). "Even in the cases where GEPs of a CB and ST did not agglomerate, the expression levels of the ER and progesterone receptor as well as ERBB2 measured in the CB were also representative for the whole tumor." (PMID 16919157, 2006). "Increasing tumour size and negative progesterone receptor status also retained significance in the multivariate model." (PMID 16859523, 2006). "A negative hormone receptor status (i.e. both ER and PgR negative) was observed more frequently in tumours overexpressing HER2 (62%) than in HER2-negative (32.5%) tumours." (PMID 15970926, 2005). "This resulted in three tumours changing their ER classification (positive to negative or vice versa), while seven specimens showed re-classification of their overall PgR score after chemotherapy." (PMID 15611798, 2005). "In this study, the independent markers that distinguished BRCA1 carrier tumours from familial non-BRCA1/2 tumours were earlier age of diagnosis, negative PgR status and higher grade." (PMID 15642173, 2005). "Recent studies have found that oestrogen-only users had decreased odds of being diagnosed with distant disease and that tumours in women having used the combined oestrogen–progestin HRT regimens were more often both oestrogen- and progesterone-receptor positive." (PMID 15238982, 2004). "The serum CYFRA 21-1 levels of the 77 PgR-positive tumours were not different from those of the 78 PgR-negative tumours (median values: 1.4 vs 1.4 ng ml−1, respectively; P=0.6762)." (PMID 15280913, 2004). "In the patient group presenting with a progesterone receptor-negative tumour, the survival rate of the MMP-2-positive cases was 58% while it was 95% in MMP-2-negative cases after 10 years of follow-up (P=0.005)." (PMID 14520459, 2003). "Patients with ER-positive or PgR-positive tumours had a more favourable response rate (OR=3.73 and OR=1.73, respectively) than patients with ER-negative or PgR-negative tumours (OR=1)." (PMID 12671709, 2003).
tumor (continued). "PMN-E levels were negatively related with ER (rs=−0.20, P<0.001) and PgR (rs=−0.19, P<0.001), but were not significantly related with tumour size (P=0.74) or grade (P=0.11), or with the lymph-node status of the patient (P=0.48)." (PMID 12671709, 2003). "Whilst the degree of reduction varied widely between different tumour pairs, this was not related to pathological changes or degree of tumour shrinkage, ER level or PgR status." (PMID 12177804, 2002). "It should be noted that in this setting, PgR status in the pre-treatment biopsy was not predictive of clinical or pathological responses: for example, four of the five PgR-negative tumours exhibited clear pathological responses with treatment." (PMID 12177804, 2002). "VEGF levels were higher in PgR-negative, compared with receptor-positive tumours (rs=−0.090, P=0.035)." (PMID 12232762, 2002). "In contrast, ER and PgR status, patient age and histological grade were of no prognostic significance in this subset of tumour samples." (PMID 12439718, 2002). "Of the five PgR-negative tumours, four (80%) showed evidence of pathological response and none changed their PgR status." (PMID 12177804, 2002). "It should be noted that the decrease in PgR occurred in both tumours, with and without clinical or pathological response." (PMID 12177804, 2002). "A high level of VEGF (⩾0.53 ng mg−1 protein) was shown to independently predict a short RFS and OS in patients with node-negative breast cancer, in addition to age, tumour size and PgR." (PMID 12232762, 2002). "Lymph node metastases were found in 85% of patients with lymphovascular invasion in their tumours as compared to only 15.4% of those without and in 45.5% of oestrogen and progesterone receptor-positive tumours." (PMID 10471048, 1999). "MRP expression was not related to patient's age, menopausal status, tumour size, differentiation grade, oestrogen and progesterone receptor level or lymph node involvement." (PMID 9275026, 1997). "In this study, the expression of nm23-H1 and -H2 was not correlated with stage, metastasis, tumour size, myometrial invasion, oestrogen receptor, progesterone receptor or menopause." (PMID 8519661, 1995). "Oestrogen or progesterone receptor negativity, aneuploidy and tumour diameter exceeding 20 mm were studied as negative prognostic signs in life table analyses and Cox proportional hazards models of corrected survival." (PMID 8123483, 1994). "In the subset of 83 tumours with intermediate levels of ER and PgR (both > or = 10, but not both > or = 75 fmol mg-1 protein), PS2 was positively related with the length of PFS (P < 0.01) and PRS (P < 0.05)." (PMID 7981080, 1994). "High body weight was correlated with advanced tumour stage (P = 0.002) and progesterone receptor (PR) positivity (P = 0.01), but not with the presence of oestrogen receptor (ER P = 0.21)." (PMID 3219275, 1988). "Additionally, tumor cells exhibited a luminal A-like phenotype, with positive estrogen receptor (ER) and progesterone receptor (PR) expression and negative human epidermal growth factor receptor 2 (HER2) status." (PMID 40909459, 2025). "This includes its effectiveness in breast cancer cells representing tumor phenotypes such as Estrogen Receptor-positive (ER +), Human Epidermal Growth Factor Receptor Type 2 (HER-2) enriched, and Triple Negative (TN), which lacks expression of ER, Progesterone Receptor (PR), and HER-2." (PMID 40608162, 2025). "Pathologically, small, uniform tumor cells resembling proliferative endometrial stroma grow in a spiral pattern around small vessels, with round or oval nuclei, sparse cytoplasm, and are characterized by CD10, estrogen receptor (ER), and progesterone receptor (PgR) positivity." (PMID 40144425, 2025).
tumor (continued). "In our study of 1298 patients, the nomogram accurately predicted low-risk results for most individuals but underestimated risk in some patients with aggressive tumor features, such as high tumor grade, lack of progesterone receptor expression, and high Ki-67 levels." (PMID 41008925, 2025). "Considering the following factors, the patient strongly desired treatment other than surgery: The tumor tissue expressed ER and PgR, she was not menopausal and had preserved ovarian function; hence, further treatment was aimed at suppressing estrogen and progesterone." (PMID 40291187, 2025). "Additionally, the tumour was negative for estrogen receptor and progesterone receptor, ruling out a potential metastatic spread from a uterine source." (PMID 40433213, 2025). "Hypermethylation of the glutathione S-transferase mu 2 (GSTM2) promoter has been identified as a potential biomarker for aggressive tumor behavior and may contribute to the progression of estrogen receptor (ER)-and progesterone receptor (PR)-negative BRCA." (PMID 41278297, 2025). "The tumor was ER and PgR-negative, HER2 3+ and had a Ki-67 index of 27%." (PMID 40843868, 2025). "In this case, the tumor’s morphological features, positive immunohistochemical staining for progesterone receptor (PR) and carcinoembryonic antigen (CEA), and negative estrogen receptor (ER) and human epidermal growth factor receptor 2 (HER2) are characteristic." (PMID 41294696, 2025). "mRNA levels of ESR1 and PGR had bimodal distributions, suggesting there may be a clear discrimination between patients with hormone receptor-positive and receptor -negative tumours at the mRNA level." (PMID 38587062, 2024). "Their study found a positive association between higher prediagnostic T3 levels and increased tumor size, lymph node metastases, and negative estrogen and progesterone receptor status, highlighting the intricate interplay between thyroid hormones and cancer progression." (PMID 38269223, 2024). "Moreover, PGR knockdown restrained PDAC cell survival and tumor growth both in vitro and in vivo." (PMID 38424455, 2024). "Moreover, RAB17 expression was strongly correlated with tumor stage, histological grade, time of last pregnancy, erb-b2 receptor tyrosine kinase 2 (ERBB2) expression, estrogen receptor (ER) levels, progesterone receptor (PR) levels, and the Ki67 index in patients with EC." (PMID 39242574, 2024). "The mammography and breast Ultrasound (US) showed a suspicious neoplasm of 37 × 17 mm, and the needle-biopsy demonstrated a high-grade (G3), estrogen receptor (ER)-positive (40%), progesterone receptor (PgR)-negative, Ki67 = 40%, c-erb-2 protein-positive (3+) invasive ductal breast cancer." (PMID 38785498, 2024). "Immunohistochemistry showed the tumor was diffusely strongly positive for estrogen receptor (ER), and about 20% of tumor cells were positive for progesterone receptor, while her-2 protooncogene expression was negative and ki-67 index was 20%; negative for CK5/6, P63 and calponin." (PMID 37933028, 2023). "Early recurrence was associated with larger tumors (mean 4.2 cm vs. 2.9 cm, p < 0.0001), higher incidence of > 3 positive nodes (32.4% vs. 9.11%, p > 0.0001), and more aggressive tumor biology (low/negative progesterone receptor expression, higher grade, and higher Ki67)." (PMID 37464134, 2023). "Interestingly, 10 tumor pairs switched tumor marker status in the transition from PT to IBTR (ER: n = 1; PgR: n = 6; Ki-67: n = 7), which were in most cases validated by proteogenomics (RNA level: ER n = 1/1, PgR n = 4/6, Ki-67 n = 1/7; protein level: PgR n = 4/6, Ki-67 n = 1/7)." (PMID 36732562, 2023). "Since PgR expression in the cancer stroma is a good prognostic marker, PgR-positive CAFs may be a type of tumor-suppressive CAF and not quiescent fibroblasts." (PMID 37509283, 2023). "Interestingly, the increase in signature 3 was associated with absence of hormonal receptors (ER p = 0.074; PgR p = 0.021), and high tumor grade (p = 0.047)." (PMID 36732562, 2023).